ADAM17 (ADAM metallopeptidase domain 17)
Diseases named in the same sentence as ADAM17 in open-access papers (continued):
Sharing a sentence is not in itself a finding about the gene and the disease.
prostate carcinoma (17 papers, 2005 to 2025). A carcinoma that arises from epithelial cells of the prostate gland. "ADAM17-mediated cleavage of TGF-α also plays a role in prostate cancer, where the overexpression of ADAM17 correlates with invasive characteristics, the activation of the EGFR-MEK-ERK pathway, and increased MMP-2 and MMP-9 levels." (PMID 40427200, 2025). "CD166 is a marker of prostate cancer progression with a role in metastasis to bone, and is known to be shed from prostatic cancer cells by the action of the sheddase ADAM17, which was also detected with abundant biotinylated peptides." (PMID 38053024, 2023). "ADAM17 has also been shown to be implicated in the proteolytic cleavage of TGFβRI, leading to aberrant TGF-β signaling in prostate cancer cells." (PMID 35625561, 2022). "Further study proved that a disintegrin and metalloproteinase ADAM17 as an executor of E-cadherin cleavage mediated the inhibitory regulation of CD82 in E-cadherin shedding in prostate cancer." (PMID 33204367, 2020). "Here, the authors show that loss of PTEN in prostate cancer models results in increased Notch1 cleavage and activation through CUX1-mediated transactivation of ADAM17." (PMID 27941799, 2016). "Altogether, our findings describe a novel pro-tumorigenic network that links PTEN loss to ADAM17 and NOTCH signalling, thus providing the rational for the use of γ-secretase inhibitors in advanced prostate cancer patients." (PMID 27941799, 2016). "Overexpression of ADAM species is known in tumor cell lines, for example, ADAM10, ADAM12 and ADAM15 in hematological malignant tumor cell lines, and ADAM9, ADAM10, ADAM15 and ADAM17 in prostate cancer cell lines." (PMID 16277668, 2005). "This interesting data implied that the activity of ADAM17 may be mostly blocked by CD82 in prostate cancer cells." (PMID 33204367, 2020). "Recently, it has been reported that a disintegrin and metalloprotease 17 (ADAM17) could induce prostate cancer cell proliferation via EGFR/PI3K/Akt pathway activation." (PMID 24311896, 2013). "The release of mature epiregulin occurs via proteolytic cleavage by ADAM17, MMP2, and MMP9 which are increased in castration-resistant prostate cancer cells." (PMID 36994208, 2023). "ADAM17 targets MMP2 and MMP-9 via EGFR-MEK-ERK pathway activation to promote prostate cancer cell invasion." (PMID 36172139, 2022). "According to previous reports, miR-152-3p targets ADAM17 and TMEM97 in non-small cell lung cancer and prostate cancer, inhibiting the activity of tumor cells 30,31." (PMID 32913475, 2020). "In addition, the stimulation of ADAM17 activity promotes cell migration and the TGF-α/EGFR pathway in invasive hypoxia prostate cancer cells." (PMID 34746310, 2021).
type 2 diabetes (17 papers, 2007 to 2025). "This study suggested that in patients with type 2 diabetes, the deregulation of ADAM17 and MMP9 activities in atherosclerotic plaques is associated with an impaired expression of TIMP3 via SIRT1." (PMID 38304233, 2023). "Interestingly, increased ADAM17 is associated with type II diabetes." (PMID 33922918, 2021). "Authors showed that at level of human carotid atherosclerotic plaques, TIMP3 was significantly impaired in patients with type 2 diabetes, leading to A Disintegrin And Metalloproteinase (ADAM17) and MMP9 overactivity." (PMID 38304233, 2023). "Moreover, low-dose Pioglitazone (PIO), a peroxisome proliferator-activated receptor (PPAR)γ agonist, reduced ADAM17 enzymatic activity in human skeletal muscle, and that these effects were associated with an improvement in glyco-metabolic control and inflammatory state in type 2 diabetes." (PMID 34181080, 2021). "The present data is consistent with the idea that Type 2 diabetes LDL could increase ADAM17 activity in THP-1 monocytes, and their ability to shed TNF-α and VCAM-1." (PMID 17714581, 2007). "Therefore, decreasing ADAM17 at the endothelial level may have a renoprotective effect and could be a possible translational strategy for patients with incipient type 2 diabetes." (PMID 35008648, 2021). "In vitro, Type 2 diabetes LDL promoted the expression of the MMP-1, MMP-9, ADAM28, ADAM17 and ADAM15 genes compared to control LDL." (PMID 17714581, 2007). "ADAM gene expression in Type 2 diabetes LDL treated cells was significantly higher compared to control LDL treated cells for a] ADAM 28 after 4 and 24 hours at higher LDL concentrations b] ADAM17 after 4 hours at higher LDL concentrations c] ADAM 15 at 4 hours at higher LDL concentrations." (PMID 17714581, 2007). "Moreover, transgenic mice with ADAM17 overexpression presented increased macrophage infiltration and fibrosis when fed an HFD, whereas ADAM17 gene silencing in visceral macrophages improved AT inflammation and type 2 diabetes." (PMID 40806445, 2025). "An increase in ADAM17-mediated shedding activity and decrease in its substrate angiotensin-converting enzyme 2 (ACE2) have been observed with the progression of type 2 diabetes mellitus (T2D), suggesting the importance of this mechanism in the disease." (PMID 33801681, 2021). "Interestingly, elevated plasma concentration of two ADAM17 substrates such as TNFR1 and TNFR2 have been recently found to predict Stage 3 Chronic Kidney Disease and End Stage Renal Disease in patients with type 1 and type 2 diabetes, respectively, even in the absence of proteinuria." (PMID 34181080, 2021).
colitis (16 papers, 2013 to 2026). Inflammation of the colon. "Our data hence establish that like ADAM17, loss of iTAP/Frmd8 exacerbates experimental colitis in vivo and impairs the capacity of recovery after the insult." (PMID 36720499, 2023). "In a murine model of colitis-associated premalignant cancer, elevated expression of ADAM17, IL-6, gp130 and sIL-6R in lamina propria macrophages were reported." (PMID 32867390, 2020). "ADAM17 knockout mice are not viable, but a genetically engineered mouse that expresses very low levels of ADAM17 in all tissues does exist and shows increased susceptibility to dextran sulfate sodium-induced colitis." (PMID 31507587, 2019). "Several studies have demonstrated that Adam17 and Egfr-deficient mice are more susceptible to colitis induced by oral administration of DSS." (PMID 29312533, 2017). "Using this system, we investigated whether the protective effects of hypomorphic ADAM17 extended beyond colitis-associated necroptosis." (PMID 29560122, 2018). "In a mouse model of acute colitis, iRhom2/ADAM17 activity drove damaging inflammation and impaired epithelial integrity through ADAM17 shedding of cell adhesion molecules." (PMID 41015904, 2025). "In DSS-induced colitis mice, ligustilide significantly reduced ADAM17 protein expression by Western blot and immunohistochemistry analysis." (PMID 40904624, 2025). "Consistent with this ADAM17 phenotype, iTAP/Frmd8 KO mice were more prone to worsened indicators of disease triggered by a model of acute DSS-induced colitis, including more pronounced body weight loss and colon shortening." (PMID 36720499, 2023). "The most studied ADAMs in IBD was Adam17, associated with EGFR and STAT3 signaling pathways crucial for the pathogenesis of colitis, high epithelial expression of which positively correlated with cell proliferation and goblet cell number in UC patients." (PMID 36901742, 2023). "Leads to a decrease in miR-143/145a, miR-148a and miR-152 in colonocytes with a consequent increase in ADAM17 expression protein (these miRs regulating ADAM17) and aggravates colitis." (PMID 35886959, 2022). "The Western diet has been shown to lead to a decrease in miR-143/145a, miR-148a and miR-152 in colonocytes with a consequent increase in ADAM17 (a disintegrin and metalloprotease 17) expression protein and colitis aggravation." (PMID 35886959, 2022). "ADAM17 hypomorphic ADAM17ex/ex mice were shown to be hypersensitive to DSS-induced colitis due to a failure to induce EGF-R signaling, which was needed for intestinal regeneration." (PMID 31694340, 2019). "ADAM17 is a central regulator of intestinal homeostasis, and mice hypomorphic for ADAM17 are highly susceptible to DSS-induced colitis." (PMID 29560122, 2018). "In contrast to ADAM17 wildtype (WT) mice, ADAM17ex/ex mice show a dramatically increased susceptibility to dextran sulfate sodium (DSS)-induced colitis." (PMID 29560122, 2018). "In conclusion, our data show that the effect of PACS-2 on ADAM17-mediated EGFR activation has negligible impact on DSS-induced colitis and the ApcMin model of cancer." (PMID 29312533, 2017). "Likewise, we observed that ligustilide obviously weakened ADAM17 expression in colitis mice and LPS-activated macrophage." (PMID 40904624, 2025). "Hence, ADAM17 mutants are sensitized to intestinal damage driven by an experimental dextran sulfate sodium (DSS)–induced colitis model." (PMID 36720499, 2023). "Moreover, the data we have obtained in ADAM17ex/ex MEF show that the protection conferred by hypomorphic ADAM17 is not limited to DSS-induced colitis but also encompasses TNF-induced necroptosis." (PMID 29560122, 2018). "Importantly, ADAM17-mediated EGFR activation is essential for gut regeneration, and Adam17 and Egfr-deficient mice are more susceptible to colitis induced by oral administration of the sulfated polysaccharide dextran sodium sulfate (DSS)." (PMID 29312533, 2017).
colitis (continued). "Also, while loss of ADAM17 has been shown to significantly impact both inflammation and regeneration in the DSS-induced model of colitis, PACS-2-deficient animals only displayed indications of delayed regeneration in this model." (PMID 29312533, 2017). "Consistent with this notion, ADAM17ex/ex mice are more profoundly sensitized to DSS-induced colitis than appears to be the case in iTAP/Frmd8 KO mice, suggesting that the titer of mature ADAM17 available may be higher in iTAP/Frmd8 KO mice than in ADAM17ex/ex mice." (PMID 36720499, 2023). "Mice with systemic deletion of ADAM17 (Adam17flox/floxMx1-Cre knock-in mice, in which temporal systemic deletion of ADAM17 is obtained by injection of plpC–polyinosinic polycytidylic acid) developed more severe dextran sulfate sodium-induced colitis when compared to control littermates." (PMID 33579029, 2021). "The disintegrin metalloprotease ADAM17 has a critical role in intestinal inflammation and regeneration in mice, as illustrated by the dramatically increased susceptibility of ADAM17 hypomorphic (ADAM17ex/ex) mice to dextran sulfate sodium (DSS)-induced colitis." (PMID 29560122, 2018). "While the precise mechanisms governing ADAM17- and EGFR-mediated protection against DSS-induced colitis remain unknown, the ErbB ligands and known ADAM17 substrates amphiregulin (AREG), epiregulin (EREG), and transforming growth factor (TGF)-α appear to be key effectors." (PMID 29312533, 2017).
diabetic nephropathy (16 papers, 2013 to 2025). "Moreover, renal TIMP3 expression was significantly reduced, supporting earlier findings that the loss of endogenous ADAM17 inhibitor exacerbates diabetic nephropathy." (PMID 23646149, 2013). "There is a large amount of evidence for ADAM17 playing a role in the pathogenesis of diabetic nephropathy." (PMID 35207132, 2022). "In agreement, Casagrande and colleagues demonstrated that Timp3-overexpression in myeloid cells protected mice from streptozotocin-induced diabetic nephropathy at the same extent as ablation of ADAM17 in podocytes." (PMID 35207132, 2022). "Our group demonstrated in type 1 diabetic mice that Adam17 deletion in proximal tubular cells protects from diabetic kidney lesions, suggesting a potential therapeutic strategy for the treatment of diabetic nephropathy." (PMID 34884897, 2021). "Since endothelium dysfunction has been posited to play an important role in the pathogenesis of diabetic nephropathy, we aimed to study the effect of conditional endothelial Adam17 deletion on an obese pre-diabetic mouse model." (PMID 35008648, 2021). "Loss of tissue inhibitor of metalloproteinase 3 (TIMP3), an endogenous inhibitor of ADAM17, has been shown to exacerbate diabetic nephropathy." (PMID 23646149, 2013). "In the present study, we investigated whether ADAM17 may play a role in the pathogenesis of diabetic kidney disease via the induction of glomerular injury." (PMID 39859443, 2025). "Interestingly, the role of ADAM17 as an upstream regulator of Nox4 was recently reported to be involved in extracellular matrix accumulation during diabetic nephropathy." (PMID 32024241, 2020). "Our data aligns with recent findings in other diseases, such as diabetic kidney disease (DKD), where SIRT1 activation mitigates pathological changes by modulating key downstream targets, including TIMP3 and ADAM17." (PMID 39682757, 2024). "Upregulation of ADAM17 has been shown to contribute to diabetic nephropathy and, in an animal model of non-obese, insulin-resistant diabetes blocking of ADAM17 activity restored insulin sensitivity." (PMID 32024241, 2020). "In diabetic nephropathy, enhanced PT shedding of ACE2 fragments via ADAM17 could increase Ang II degrading capacity in the urine, and could serve as a biomarker of early kidney injury." (PMID 24454948, 2014).
non-small cell lung carcinoma (15 papers, 2012 to 2025). A group of at least three distinct histological types of lung cancer, including non-small cell squamous cell carcinoma, adenocarcinoma, and large cell carcinoma. "ADAM17 is predominantly activated in disease states associated with infection, autoimmunity, cardiovascular diseases, neurodegeneration, and cancer, in particular non-small cell lung carcinoma (NSCLC) and head-and-neck squamous cell carcinoma (HNSCC)." (PMID 32050662, 2020). "ADAM17 has also been proposed as a target for radiosensitization in non-small cell lung cancer, suggesting that repurposing ADAM17 inhibitors could serve as short-term adjuvants to improve outcomes in radiotherapy settings." (PMID 39062581, 2024). "Interestingly, C-X-C chemokine receptor type 4 (CXCR4), a receptor widely reported to regulate extramedullary myeloma, was found to induce VCAM1 secretion in non-small cell lung cancer via the regulation of the metalloproteinase, ADAM17." (PMID 37568580, 2023). "However, the efficacy of radiotherapy for non-small cell lung cancer was enhanced when blockade of ADAM17 function with the neutralizing antibody." (PMID 36466812, 2022). "Moreover, X-ray increases the ADAM17 activity in non-small cell lung cancer in a time and dose-dependent manner, thereby enhancing the cleavage of its substrates on the cell surface." (PMID 36359750, 2022). "Corresponding to our data, expression patterns of miR-152 and ADAM17 were opposite in HUVEC cells and expression levels likewise inversely correlated in non-small cell lung cancer tissues." (PMID 36293469, 2022). "Here we investigate in non-small-cell-lung-cancer (NSCLC) cells a novel link between IR-enhanced ADAM17 activity and the non-canonical pathway of EphA2 in the cellular stress response to irradiation." (PMID 36998455, 2023).
Arthritis (14 papers, 2012 to 2025). Inflammation of a joint. "Furthermore, dysregulation of ADAM17 is strongly linked to numerous common pathological conditions, such as asthma, arthritis, cancer and fibrosis." (PMID 40077919, 2025). "Previous studies have reported that TMI-1 is effective and beneficial in treating arthritis and neoplasm via inhibition of ADAM17/MMPs." (PMID 35250589, 2022). "The expression of ADAM17 in mouse articular cartilage is positively correlated with the development of arthritis, and its deletion attenuates articular cartilage degeneration." (PMID 36466812, 2022). "TMI-1 has been successfully used in mouse models of arthritis and kidney diseases to target and inhibit ADAM-17-mediated TNFα (Tumor Necrosis Factorα) and TGFα (Transforming Growth Factorα) release, respectively." (PMID 23028451, 2012). "ADAM17 is highly expressed or upregulated in cancer and other inflammation-related diseases, including kidney disease, sepsis, cicatrization, diabetic retinopathy, myocardial fibrosis, aortic dissection, arthritis and atherosclerosis." (PMID 36466812, 2022). "TIMP-3 plays a protective role in arthritis by inhibiting ADAM17, thereby dampening TNF signalling." (PMID 35207132, 2022). "Furthermore, iRhom2-dependent trafficking of the IL-6R sheddase ADAM17 and its activity on myeloid cells was shown to be involved in development of experimental arthritis in mice." (PMID 31694340, 2019). "We propose that ADAM-17 plays roles in mediating arthritis by this multistep process." (PMID 30071898, 2018). "Recently, a specific inhibitor of ADAM17 was efficacious in a collagen-induced arthritis model, suggesting that targeting the enzyme for arthritis may be beneficial in the clinic." (PMID 29230082, 2017). "An ADAM17 inhibitor may be beneficial in arthritis and other inflammatory processes by regulating the glycoprotein's cleavage, thereby preventing microplatelet formation." (PMID 29230082, 2017). "A dual ADAM17/MMP inhibitor, compound 16 (TMI-1), demonstrated superior in vitro potency against ADAM17 and in cellular assays, as well as oral bioactivity in an in vivo model of TNF-α production and a collagen-induced arthritis model." (PMID 41050403, 2025). "Conversely, by targeting ADAM17, there is an overexpression of TIMP-3 dampened TNF-release that ameliorated the development of arthritis in a murine model of the disease." (PMID 33673623, 2021). "While the ADAM17/TNF/TNFR1 axis plays a key role in defending the organism against invading pathogens, when deregulated, this signalling pathway can lead to autoimmune and inflammatory diseases, including arthritis." (PMID 35207132, 2022).